ATP7B (ATPase copper transporting beta)
Diseases named in the same sentence as ATP7B in open-access papers (continued):
Sharing a sentence is not in itself a finding about the gene and the disease.
Wilson disease (continued). "Wilson's disease is a rare genetic disorder characterized by abnormal copper metabolism due to mutations in the ATP-7B gene." (PMID 39176358, 2024). "Biallelic mutations in the ATP7B gene are known to cause Wilson’s disease, which is characterized by accumulation of intracellular Cu and manifestation of liver symptoms such as acute hepatitis, hepatomegaly, jaundice, and cirrhosis." (PMID 38424191, 2024). "Testing for mutations in the ATP7B gene confirmed the presence of 2 pathogenic mutations, which is a hallmark of Wilson disease." (PMID 38306527, 2024). "Wilson’s disease is a hereditary disorder of copper metabolism resulting from mutations in the ATP7B gene." (PMID 38904034, 2024). "Our findings help to understand the neuropathology of human Wilson disease, which is caused by inactivating mutations in ATP7B." (PMID 36626371, 2023). "Wilson’s disease, also referred to as hepatolenticular degeneration, is an autosomal recessive genetic condition caused by mutations in the ATP7B gene." (PMID 37629187, 2023). "Wilson disease (WD) is an autosomal recessive genetic disorder caused by mutations of ATP7B, a copper transporter, which results in impaired copper clearance." (PMID 37342740, 2023). "Wilson disease (WD) is a rare autosomal recessive disorder of copper metabolism caused by pathogenic variants in the ATP7B gene, which encodes a P-type copper-transporting ATPase and mainly is expressed in hepatocytes." (PMID 37707949, 2023). "Wilson’s disease (WD) is a rare autosomal recessive disease caused by mutations in the ATP7B gene, leading to impairment in copper excretion and subsequent accumulation primarily in the liver and brain." (PMID 37809179, 2023). "Wilson disease (WD) is another disorder of Cu homeostasis caused by mutations in the Cu-transporter ATP7B." (PMID 36626371, 2023). "Mutations in the genes encoding ATP7A and ATP7B cause inherited disorders of Cu metabolism, known as Menkes’ disease and Wilson’s disease, respectively." (PMID 38139406, 2023). "Wilson’s disease (WD) is a rare autosomal recessive disease caused by mutations in the copper transporter gene, ATP7B, resulting in copper accumulation mainly in the liver, along with some other organs." (PMID 36899921, 2023). "In Wilson’s disease hiPSCs, the mutation in R778L (arginine 778 lysine) in ATPase copper transporting beta (ATP7B) was induced; this has application in drug screening and finding disease model mechanisms for Wilson disease." (PMID 36838970, 2023). "The genetic test for Wilson’s disease showed a compound heterozygosity at exon 6 and exon 8 of the ATP7B gene (both mutations were characteristic of the Spanish population)." (PMID 37759957, 2023). "Two patients were identified with homozygous or compound heterozygous ATP7B mutations, consistent with the diagnosis of Wilson disease." (PMID 37237429, 2023). "Wilson’s disease (hepatolenticular degeneration) is an autosomal recessive genetic defect of copper (Cu) metabolism that originates from mutations in the ATP7B gene." (PMID 37759956, 2023). "While ATP7A mutations cause Cu deficiency resulting in developmental delay, hypotonia, and nervous system deterioration, mutations in ATP7B cause Wilson’s disease that results in excessive Cu accumulation, mainly in the liver and brain." (PMID 36818345, 2023). "The common mutation spectrum of GJB2 and SLC26A4 in this study was consistent with previous literature reports of the Chinese population, while the mutation spectrum of ATP7B was inconsistent with a research report of Chinese patients with Wilson's disease." (PMID 37031186, 2023). "Mutations in ATP7A and ATP7B genes cause inherited disorders, known as Menkes and Wilson diseases, respectively." (PMID 36818345, 2023). "Wilson’s Disease is a congenital autosomal disorder of copper metabolism produced by a mutation in the ATP7B copper transporter gene and has a ratio of around 1/30,000–1/100,000." (PMID 37048674, 2023).
Wilson disease (continued). "Wilson disease (WD) is an autosomal recessive copper metabolism disease caused by mutations in the ATP7B gene, which encodes a copper-transporting P-type ATPase to convey copper for synthesising ceruloplasmin (Cp)." (PMID 36915635, 2023). "In contrast, a mutation in the ATP7B gene results in Wilson's disease, which causes copper accumulation and toxicity in the brain and liver as ATP7B is crucial for copper transport from the liver into bile." (PMID 37905492, 2023). "Wilson’s disease (WD) is a genetic disease caused by mutations on the Atp7b gene coding for a copper carrier protein in charge of the excretion of excess copper from the liver." (PMID 38140060, 2023). "For example, in Saudi Arabia, in 50% of patients with Wilson’s disease, pathogenic variants were detected in three exons (exons 8, 19 and 21) of the ATP7B gene." (PMID 37046505, 2023). "A diagnosis of Wilson’s disease can be made in a person who has two pathogenic (or likely pathogenic) variants of ATP7B detected by molecular genetic testing." (PMID 37046505, 2023). "Wilson’s disease (WD) is a rare autosomal recessive (AR) disorder resulting from mutations in the ATP7B gene, which is responsible for the encryption of transmembrane copper transporting ATPase." (PMID 36900037, 2023). "The reduction of circulating holo-CP concentrations is one of the early symptoms of Wilson’s disease caused by the impaired transfer of copper via ATP7B to CP and concomitant hepatic copper accumulation." (PMID 37311819, 2023). "Wilson's disease (WD) is a genetic disease caused by mutation of the ATP7B gene, which leads to disordered copper metabolism." (PMID 37483763, 2023). "ATP7B, a P-type ATPase involved in copper secretion, played a pivotal role as a copper transporter, whose mutation caused Wilson’s disease due to excess copper accumulation-induced chronic liver diseases." (PMID 37180167, 2023). "The etiology of Wilson’s disease is ATP7B gene mutation that primarily reduces the secretion of copper with concomitant hepatocyte damage and hypofunction." (PMID 37525189, 2023). "Hepatolenticular degeneration, also known as Wilson disease (WD), is a copper metabolism disorder caused by mutations in the gene ATPase copper transporting beta located on chromosome 13q14." (PMID 36800617, 2023). "Wilson’s disease (WD) is an autosomal recessive inherited disorder of copper metabolism caused by mutations in the ATP7B gene." (PMID 37152597, 2023). "This is the first association of the CBS-PNFA phenotype with the most common ATP7B pathogenic variant p.H1069Q, previously linked to Wilson’s disease, and early onset Parkinson’s disease." (PMID 36553628, 2022). "Mutations of the genes involved in hemochromatosis, alpha 1-antitrypsin deficiency (SERPINA1), glycogen storage diseases (G6PC, SLC37A4), porphyries (HMBS, UROD), tyrosinemia (FAH), and Wilson’s Disease (ATP7B) increase the susceptibility to HCC." (PMID 36676960, 2022). "Wilson’s disease (WD) is an autosomal recessive disorder of copper metabolism caused by ATP7B (encoding a copper-transporting P-type ATPase) variants that shows various characteristics according to race and geographical region." (PMID 35220961, 2022). "In patient 45, NGS revealed a homozygous VOUS variant in ATP7B, previously reported to cause an attenuated phenotype of Wilson disease." (PMID 35626323, 2022). "Wilson’s disease (WD) is also thought to be a monogenetically caused metabolic disorder, with more than 1000 mutations of the ATP7B gene on chromosome 13q14.3." (PMID 36291607, 2022). "Wilson disease (WD) is a genetic disorder of copper homeostasis, caused by deficiency of the copper transporter ATP7B." (PMID 36092366, 2022). "In Wilson disease, the gene coding for ATP7B is mutated, leading to copper overload, firstly, in the liver and the brain." (PMID 36359796, 2022).
Wilson disease (continued). "Wilson’s disease (WD) is a hereditary systemic Cu toxicosis resulting from mutations in the gene coding for ATP7B which is responsible for Cu transport and efflux from liver cells." (PMID 35625641, 2022). "Mutations in ATP7B lead to Wilson’s disease, which is characterized by copper accumulation in the liver and brain that can result in potentially fatal hepatoneurological symptoms if left untreated." (PMID 36070320, 2022). "On the Wilson disease ontology report page, the result table for human shows data for cell lines, variants, and genes, including ATP7B, annotated to the term in the Disease Ontology." (PMID 34741192, 2022). "Mutations in the gene coding for ATPase copper transporting beta polypeptide (ATP7B) cause Wilson's disease, located on chromosome 13." (PMID 35371680, 2022). "The ATP7B gene mutation, resulting in copper overload and autistic copper homeostasis, is the cause of Wilson’s disease." (PMID 36567939, 2022). "Wilson disease is an inherited disorder of copper metabolism due to mutations in ATP7B and is an attractive target for gene therapy." (PMID 36092366, 2022). "Wilson's disease (WD) is an autosomal recessive disease related to ATP7B mutations causing copper transport disorder." (PMID 36282481, 2022). "Mutations that impair transport activity or disrupt intracellular targeting of ATP7B cause Wilson disease and chronic copper toxicosis." (PMID 35763513, 2022). "Wilson’s disease (WD) is a recessive genetic disease caused by mutations in the copper transport gene ATP7B on chromosome 13." (PMID 35706848, 2022). "Wilson’s disease (WD) is an autosomal recessive genetic disorder due to a mutation of the ATP7B gene, resulting in impaired hepatic copper excretion and accumulation in various tissues." (PMID 35566651, 2022). "Wilson disease is characterized by copper metabolism disorder caused by the mutations of ATP7B gene, manifested as decreased ceruloplasmin and increased urine copper, which can simultaneously or solely involve the liver, eyes, and nervous system." (PMID 36381061, 2022). "Activation of autophagy, observed in liver tissues from patients with Wilson disease and from ATP7B-deficient animals, protects hepatocytes from copper-induced apoptosis." (PMID 36238639, 2022). "For example, MTF1 promotes ATP7B expression by binding to the MRE in the promoter region of ATP7B to promote Wilson’s disease caused by copper overload." (PMID 35990673, 2022). "Wilson’s disease (WD) is an autosomal recessive disorder of copper metabolism caused by mutations in the ATP7B gene, which is located in the long arm of chromosome 13 (locus 13q14.3)." (PMID 37361868, 2022). "Although there are a number of other genes that serve as biomarkers and modifiers of the disease, Wilson disease is primarily a monogenic disease caused by mutations in the ATP7B gene." (PMID 34741192, 2022). "Wilson ́s disease (WD) is an autosomal recessively inherited disorder of copper metabolism caused by a defect of the large ATP7B gene localized on chromosome 13 which contains 20 introns and 21 exons." (PMID 35885998, 2022). "Dysregulation can cause severe diseases, for example the copper metabolism disorder Wilson’s disease, which is caused by mutations in ATP7B regulation machinery." (PMID 36070320, 2022). "Wilson’s disease (WD), also known as hepatolenticular degeneration, is a rare genetic condition due to a recessive mutation of the ATP7B gene." (PMID 35566651, 2022). "Intracellular copper overload is closely related to poor prognosis, such as in Wilson’s disease that is caused by ATP7B mutation." (PMID 36601107, 2022). "Wilson’s disease (WD) is an inherited autosomal recessive disorder of copper metabolism that is caused by a pathogenic variant in the ATP7B gene." (PMID 36210929, 2022). "Both the disease annotations imported from ClinVar and the Clinical Variants section of the human gene page give links to RGD records for individual ATP7B variants associated with Wilson disease." (PMID 34741192, 2022).
Wilson disease (continued). "Mutations in ATP7B gene give rise to Wilson’s disease, in which defects in the ATP7B-mediated biliary copper excretion cause hepatic and systemic copper overload." (PMID 36291728, 2022). "The rat Atp7b gene report page has Wilson disease annotations based on phenotypes resulting from a spontaneous mutation in Atp7b in a rat with Wilson disease features." (PMID 34741192, 2022). "The Wilson disease is an autosomal recessive rare genetic disorder in which the atp7b gene is mutated." (PMID 36359796, 2022). "Wilson's disease (WD), also known as hepatolenticular degeneration, is an autosomal recessive disorder of copper metabolism caused by an ATP7B gene mutation." (PMID 33446761, 2021). "Despite the increasing number of reports on the analysis of ATP7B variants, reports on carrier screening for Wilson's disease (WD, OMIM:277900) are rare." (PMID 34240825, 2021). "First, we performed genetic mutation screening of ATP7B, the responsible gene of Wilson disease by very long amplicon sequencing (vLAS)." (PMID 33804940, 2021). "Wilson’s disease (WD) is an inherited genetic disease with an impaired hepatic copper transport due to mutation in ATP7B which encodes the copper–transporting P-type ATPase leading to Cu accumulation in liver and extrahepatic organs." (PMID 34940728, 2021). "Wilson’s disease is an autosomal recessive inherited disease of impaired excretion and excessive accumulation of copper caused by mutations in the ATP7B gene that encodes the ATP7B copper transporter." (PMID 32433421, 2021). "Wilson disease (WD) is a rare disorder caused by mutations in ATP7B, which leads to the defective biliary excretion of copper." (PMID 34572285, 2021). "Pathogenic genetic variants in the ATP7B gene cause Wilson disease, a recessive disorder of copper metabolism showing a significant variability in clinical phenotype." (PMID 33828154, 2021). "Deleterious mutations in ATP7B are responsible for Wilson’s disease (WD), the condition when copper is accumulated in tissues, primarily liver, causing oxidative stress." (PMID 33670100, 2021). "With mutation in the ATP7B gene, Wilson’s disease results in inadequate functional copper-transporting ATPase 2, which transports copper out of the liver and prevents intracellular copper accumulation." (PMID 34631680, 2021). "First, we detected several variants in ATP7B, the responsible gene of Wilson disease, using a long PCR-based variant calling method." (PMID 33804940, 2021). "Wilson Disease (WD) is an autosomal recessive inherited metabolic disease caused by mutations in the ATPase copper transporting beta gene (ATP7B)." (PMID 33879678, 2021). "The majority of causative Wilson disease mutations has been identified in the protein coding sequence of ATP7B or its splicing sites, while data on a role of promoter alterations on Wilson disease are comparatively rare." (PMID 33828154, 2021). "The Atp7b−/− mouse carrying a homozygous mutation in the Atp7b gene was introduced as a model with which to study hepatic manifestations of Wilson’s disease." (PMID 34944677, 2021). "Wilson disease is an autosomal recessive disorder of copper metabolism caused by inactivating mutations in the ATP7B gene (Omim # 277900)." (PMID 33828154, 2021). "Wilson disease (OMIM 277900) is caused by homozygous or compound heterozygous variants affecting the ATP7B gene (OMIM 606882) on chromosome 13q14." (PMID 34439909, 2021). "Our previous study showed that some synonymous variants in ATP7B gene produced splicing disruptions, leading to Wilson disease (WD)." (PMID 33719328, 2020). "To model Wilson’s disease, we targeted exon 8 of ATP7B gene to introduce the R778L (c.2333G>T) mutation in wildtype (WT) hESCs." (PMID 32252475, 2020). "Further investigation revealed that all the autosomal recessive variants were in the ATP7B gene, which highlighted the high carrier rate of Wilson disease in our population." (PMID 32794656, 2020).
Wilson disease (continued). "Wilson disease (WD) is an autosomal recessive disorder in which copper's metabolism is altered due to pathogenic variants in the ATP7B gene." (PMID 32154060, 2020). "Loss-of-function mutations prevent ATP7B from sequestering Cu and its removal from cells leading to severe Cu toxicosis, which is known as Wilson disease." (PMID 32155756, 2020). "Next, we set out to repair a 1-bp duplication (c.1288dup, p.S430fs) in ATP7B, causing Wilson disease." (PMID 33097693, 2020). "Wilson disease is a recessive genetic disorder caused by pathogenic loss-of-function variants in the ATP7B gene." (PMID 32284880, 2020). "Particularly mutations in the human homologues crp genes ATP7A and ATP7B cause X-linked Menkes disease and autosomal recessive Wilson’s disease, respectively." (PMID 32862758, 2020). "The autosomal recessive copper accumulation disorder Wilson disease, caused by mutations in ATP7B, is characterized by copper accumulation in the liver and sometimes the brain, resulting in hepatic cirrhosis and neuronal degeneration." (PMID 33142854, 2020). "Wilson’s disease (WD) is an autosomal recessive disorder due to a mutation of the chromosome on the ATP7B gene, which codes for a copper-transporting ATPase." (PMID 33354453, 2020). "Mutation of the liver Cu exporter ATP7B is the cause of Wilson disease and is associated with Cu accumulation in different tissues." (PMID 32155648, 2020). "Wilson’s disease (WD) is a rare autosomal recessive metabolic disorder resulting from mutations in the copper-transporting, P-type ATPase gene, ATP7B gene, which encodes a copper-transporting P-type ATPase." (PMID 32485807, 2020). "Wilson’s disease hPSCs were generated by introducing a R778L mutation in the ATP7B gene (c.2333G>T) using Clustered Regularly Interspaced Short Palindromic Repeats (CRISPR)/Cas9 system into wildtype hESCs." (PMID 32252475, 2020). "Human ATP7A and ATP7B are the best studied examples of the universally conserved P1B-type ATPases and are linked to the Cu metabolism disorders Menkes disease and Wilson disease." (PMID 32962054, 2020). "Zinc has been utilized for some time now in the treatment of Wilson disease (WD), an autosomal rare disease of copper imbalance, which mainly harms brain and liver, caused by mutations in the ATP7B gene." (PMID 32784855, 2020). "As concerns COMMD1, its overexpression in HEK 293 cells was shown to enhance degradation of stably expressed ATP7B in wild type as well as Wilson disease-mutated cells." (PMID 32668621, 2020). "Wilson disease is an autosomal recessive disorder caused by mutations in the ATP7B gene coding for the copper-transporting ATPase ATP7B." (PMID 32013126, 2020). "Wilson’s disease (WD), also known as hepatolenticular degeneration, is an autosomal recessive disease of impaired copper metabolism, caused by a mutation in the ATP7B gene, encoding copper-transporting ATPase in the liver." (PMID 32062761, 2020). "Wilson disease is an inborn disorder of the copper metabolism that is caused by a defect in the P-type ATPase gene (ATP7B)." (PMID 33036164, 2020). "Wilson’s disease is caused by a mutation of the ATP7B gene resulting in decreased biliary copper excretion, hence copper accumulates in the brain resulting in multiple neurologic symptoms including parkinsonism, chorea, and dystonia." (PMID 32775036, 2020). "Wilson’s disease (WD), also known as hepatolenticular degeneration, is a copper-overload inherited disease caused by ATP7B mutations on chromosome 13." (PMID 33041766, 2020). "Wilson disease is an autosomal recessive disorder caused by inactivating mutations in ATP7B, an enzyme involved in the secretion of Cu2+ from the liver." (PMID 33143193, 2020). "Considering those published studies and databases, the prevalence rate of Wilson disease and carrier rate of ATP7B gene mutations vary across different ethnicities." (PMID 32794656, 2020).